COMP (cartilage oligomeric matrix protein)
Diseases named in the same sentence as COMP in open-access papers (continued):
Sharing a sentence is not in itself a finding about the gene and the disease.
intrahepatic cholangiocarcinoma (1 paper, 2023). A carcinoma that arises from the intrahepatic bile duct epithelium in any site of the intrahepatic biliary tree. "Against this backdrop, the prognostic significance of COMP in intrahepatic cholangiocarcinoma (iCCA) remains unexplored." (PMID 37838792, 2023). "In summary, this study investigates the expression of COMP in intrahepatic cholangiocarcinoma (iCCA) and its implications for prognostic evaluation." (PMID 37838792, 2023).
ischemic stroke (1 paper, 2020). A stroke disorder caused by obstruction of blood flow to the brain, due to thrombotic (local blood clot formation) or embolic (due to a blood clot or other material traveling from another site) event. "An increase in ADAMTS12 activity would hypothetical lead to the degradation of COMP resulting in less inhibition of thrombin and an elevated risk for ischemic stroke." (PMID 32817637, 2020).
Jaundice (1 paper, 2021). Yellow pigmentation of the skin due to bilirubin, which in turn is the result of increased bilirubin concentration in the bloodstream. "In conformity with this, circulating COMP levels were significantly greater in BA patients with non-jaundice than those in healthy controls (P < 0.001)." (PMID 34404836, 2021). "In regards to jaundice status, BA patients with jaundice showed significantly augmented circulating COMP levels when compared with those with jaundice-free and healthy volunteers (P < 0.001, P < 0.001, respectively)." (PMID 34404836, 2021).
localized scleroderma (1 paper, 2022). Localized scleroderma is the skin localized form of scleroderma characterized by fibrosis of the skin causing cutaneous plaques or strips. "COMP levels are significantly increased in the stroma of fibrotic lesions in patients with localized scleroderma, and up-regulated COMP stimulates the deposition of collagen and other matrix proteins, leading to additional fibrosis exacerbation." (PMID 36012514, 2022).
myocardial hypertrophy (1 paper, 2021). "It's worth noting that there is no relevant report about the roles of COMP, FMOD, AEBP1 and SULF1 in HOCM or even myocardial hypertrophy, implying the need for further exploration." (PMID 34362365, 2021).
osteonecrosis (1 paper, 2021). A none disease characterized by death of bone tissue due to a lack of blood supply. "This is coherent with a role of COMP in osteogenesis, and in pathological processes of non-traumatic osteonecrosis of the femoral head." (PMID 34680093, 2021).
ovarian serous cystadenocarcinoma (1 paper, 2024). A malignant serous cystic epithelial neoplasm arising from the ovary. "In addition, a positive correlation between the expression of COMP and TGFB isoforms in ovarian serous cystadenocarcinoma was observed using the online cBioPortal and the TCGA database analyzed by the firehose legacy." (PMID 38615020, 2024).
ovarian tumors (1 paper, 2024). "Taken together, we found that high stromal COMP expression in ovarian tumors was associated with unfavorable clinicopathological characteristics and shorter patient survival." (PMID 38615020, 2024). "A xenograft mouse model showed that carcinoma-associated fibroblasts (CAFs) expressing COMP stimulate the growth and metastasis of ovarian tumors through the secretion of COMP." (PMID 38615020, 2024). "Recently, a proteomics analysis showed that COMP was the most highly expressed protein in the stroma of metastatic ovarian tumors, regulated by nicotinamide N-methyltransferase." (PMID 38615020, 2024). "In our study, increased COMP expression in the ovarian tumor stroma correlated with shorter OS, serous histological subtype and more advanced clinical FIGO stages." (PMID 38615020, 2024).
pancreatic NET (1 paper, 2023). "The selection of C1QA and COMP as the preferred biomarkers implies that these proteins strongly associate with pancreatic NET and hold promise as indicators for early disease detection." (PMID 38030709, 2023). "This intriguing finding suggests that COMP may have distinct roles in the context of pancreatic neuroendocrine tumors compared to other cancer types." (PMID 38030709, 2023).
Pruritus (1 paper, 2024). Pruritus is an itch or a sensation that makes a person want to scratch. "Additionally, we analyzed and visualized the DEPs in each group of uremic pruritus patients and uremic patients without pruritus using a Venn diagram, and found a common DEP, COMP." (PMID 38577622, 2024).
pterygium (1 paper, 2022). A wedge-shaped fibrovascular lesion arising from the bulbar conjunctiva and extending to the cornea. "Among those DE-mRNAs, matrix metallopeptidase 3(MMP-3), fibronectin 1 (FN1), tenascin C (TNC), LRRC15, KRT6A, COMP, AKR1B10, and MUC5AC were significantly upregulated, which was consistent with previous studies on pterygium." (PMID 36398070, 2022).
sarcoma (1 paper, 2024). A usually aggressive malignant neoplasm of the soft tissue or bone. "Then, we analyzed the expression of biomarkers of osteoblasts (COL1A1, BGLAP and RUNX2), chondrocytes (COL2A1, COMP and SOX9) and sarcoma (POSTN and DCN), adipocyte (LPL and PPARG) and BMSCs." (PMID 39715773, 2024).
scoliosis (1 paper, 2021). A congenital or acquired spinal deformity characterized by lateral curvature of the spine. "It was confirmed again in the proband and her young sister (II-3 and II-4), who harbored a COMP mutation and suffered from mild scoliosis and hip contractions." (PMID 33748277, 2021).
Torticollis (1 paper, 2022). Involuntary contractions of the neck musculature resulting in an abnormal posture of or abnormal movements of the head. "In two patients with pseudoachondroplasia syndrome, in which odontoid hypoplasia associated with cervical spine synchondrosis causing life-threatening torticollis, Cartilage oligomeric matrix protein (COMP) gene mutation was identified." (PMID 35885576, 2022).
ventricular dilatation (1 paper, 2018). "Thus, ADAMTS-7 may change ECM components and promote ventricular dilatation by promoting COMP degradation in cardiac fibroblasts." (PMID 29523183, 2018).
tumor (77 papers, 2006 to 2026). "ADAMTS7 is a cartilage oligomeric matrix protein-cleaving enzyme involved in extracellular matrix remodeling, whose family members are also linked to tumor progression by affecting the interplay between the malignant cells and local microenvironment." (PMID 40873563, 2025). "COMP-expressing tumors had fewer infiltrating immune cells, mainly T-cells, and denser collagen fibers, a hallmark of tumor fibrosis." (PMID 38563861, 2024). "High levels of COMP were repeatedly linked to larger tumor size, metastasis, faster cancer recurrence, and shorter overall survival." (PMID 38965233, 2024). "In the entire cohort, the presence of COMP in the stroma was associated with the location of the primary tumor (p < 0.001) and a more advanced N-stage (p = 0.005)." (PMID 38563861, 2024). "TCGA, GTEx, and CCLE data showed that COMP was significantly overexpressed in 15 human cancers and was associated with tumor immune escape." (PMID 38584705, 2024). "In these cancers, COMP overexpression was associated with increased tumor growth, cancer metastasis, cancer recurrence, and overall shorter survival." (PMID 37838792, 2023). "Immunohistochemical evaluation of COMP expression in tumor tissue is a diagnostic method that has several limitations, as it is both semi-quantitative and invasive, especially for the testing of metastatic tissue." (PMID 31737569, 2019). "The authors demonstrated the presence of COMP in 16% of tumor tissue microarrays and found a significant association with COMP expression and time to metastases and to biochemical recurrence (defined as a PSA > 0.2 ng/ml)." (PMID 31413818, 2019). "This phenomenon could be attributed to the denser collagen deposits, a hallmark of tumor fibrosis observed in COMP-expressing tumors." (PMID 38563861, 2024). "Thus, the increased serum levels of COMP in those with OA led us to believe that it is possible that an association exists between serum COMP and tumor progression." (PMID 38892202, 2024). "A pancancer multiomics analysis revealed that COMP may be a potential biomarker for pan-cancer diagnosis and prognosis, as well as its overexpression is linked with tumor immune evasion." (PMID 37965307, 2023). "Moreover, COMP expression was associated with fewer tumor-infiltrating immune cells and was negatively correlated with the expression of PD-L1." (PMID 37207219, 2023). "Moreover, COMP expression is associated with advanced pathological grade, immune cell infiltration, tumor mutation burden, and microsatellite instability." (PMID 36012514, 2022). "In prostate cancer, tumor COMP expression is associated with invasion and disease progression." (PMID 36012514, 2022). "A significant shift was seen in the COMP IHC stroma expression from the primary tumor to LNM (p = 0.049), revealing that in 70% of the pairs the expression was stable but there were more pairs with a loss of COMP expression from the primary tumor to LNM than with a gain." (PMID 34884987, 2021). "Consistent with these in vitro findings, COMP-expressing xenograft tumor tissues showed enhanced EMT characteristics." (PMID 41689303, 2026). "At the mechanistic level, CRLF1 facilitates tumor progression by modulating COMP to activate the FAK/PI3K/AKT signaling cascade." (PMID 42122189, 2026). "The immune checkpoint molecule CTLA-4 demonstrated significant positive correlations with HJURP, VGF and COMP expression (p < 0.05), suggesting potential coordinated regulation of immune evasion and tumor progression pathways." (PMID 40592939, 2025). "Tumors expressing high levels of COMP had a decreased number of infiltrating immune cells in the tumor microenvironment." (PMID 38563861, 2024). "In a xenograft mouse model, the co-injection of COMP-expressing CAFs at a 3 to 1 ratio with SKOV3 cells demonstrated a remarkable escalation in tumor volumes in comparison to the co-injection of mock-transfected CAFs with SKOV3 cells." (PMID 38615020, 2024).
tumor (continued). "McNemar test was applied to compare COMP expression in tumor cells in pairs of primary tumors and lymph node metastases (n = 67)." (PMID 38563861, 2024). "A reduced number of immune cells infiltrated the tumor microenvironment when COMP expression was detected." (PMID 38563861, 2024). "Cartilage oligomeric matrix protein (COMP) is a newly reported regulator of the tumor microenvironment." (PMID 38563861, 2024). "By the end of the experiment, the tumor weight in mice co-injected with COMP-expressing CAFs was twice as high as that of tumors formed in mice co-injected with mock CAFs." (PMID 38615020, 2024). "High levels of COMP were also correlated with denser collagen fibers in the tumor stroma, indicating a stiffer and fibrotic tumor microenvironment." (PMID 38563861, 2024). "To investigate the effect of COMP expression on immune cell exclusion in CRC, we combined the COMP expression data with already available information about tumor-infiltrating immune cells." (PMID 37207219, 2023). "Further, previous studies used mainly mRNA expression data to determine COMP expression in tumors as a whole, while we detect COMP separately in tumor cells and stroma using a validated antibody." (PMID 37207219, 2023). "In the TC patients, univariate analysis showed that COMP, age, tumor size, distance metastasis, and TNM stage were correlated with OS." (PMID 37229458, 2023). "Analyses of COMP expression in relation to the clinicopathological characteristics of the patients revealed that COMP expression both by the cancer cell and in the stroma was associated with TNM- stage and grade of tumor differentiation." (PMID 37207219, 2023). "Correlations between COMP expression both in tumor cells and in the stroma and clinical characteristics, were mainly seen in tumors of the right colon." (PMID 37207219, 2023). "Immunohistochemistry was used to determine the expression levels of COMP in tumor cells and stroma in primary tumors from a cohort of 537 CRC patients." (PMID 37207219, 2023). "Kaplan-Meier analyses revealed that patients with high tumor-cell specific COMP expression had a shorter median OS of 5 years compared with 10.9 years for patients with low tumor-cell specific COMP expression (p<0.0001)." (PMID 37207219, 2023). "First, we selected 10 pairs of BC tumor and cancer-adjacent normal tissues to verify COMP and SERPINB3 gene expression by real-time PCR." (PMID 37965307, 2023). "An important role of COMP in tumor progression was also revealed in prostate cancer, hepatocellular carcinoma, urothelial cancer, and CRC." (PMID 37207219, 2023). "Tumor fibrosis was correlated with high expression of COMP in the stroma (p<0.0001), and tumors with high levels of COMP expression and denser fibrosis displayed more sparse immune cell infiltration." (PMID 37207219, 2023). "We also stained tumor sections for the core MI components COMP, FN1, CTSB, and VCAN, which were transcriptionally upregulated in PKN2KO tumors; stains were enhanced in invasive regions and in regions of connective tissue." (PMID 35081338, 2022). "Preoperative patients had much higher serum COMP levels than healthy donors, whereas serum COMP levels were significantly reduced after colectomy, indicating its potential in monitoring tumor burden." (PMID 36012514, 2022). "Upregulated genes included cartilage-associated genes (COMP, MATN3, and COL11A2), collagen- and extracellular matrix-associated genes (COL9A2, SFRP2, and SERPINE2), and tumor metastasis- and progression-associated genes (SLC38A3, FST, ITGA11, and DGKI)." (PMID 36192442, 2022). "Tumor COMP expression is also an emerging independent prognosis indicator that is correlated with clinical parameters, including the number of lymph node metastases, estrogen and progesterone receptor positivity, Ki67 status, and poor survival and recurrence." (PMID 36012514, 2022). "Immune and stromal scores were notably higher in the high-COMP subgroup, while tumor purity was lower." (PMID 36671447, 2022).
tumor (continued). "Increased COMP expression in tumor tissue is related to advanced tumor node metastasis (TNM) stage and poor prognosis in stage III and IV patients." (PMID 36012514, 2022). "Further, matched tumor tissues from the primary tumor and metastases were stained for COMP expression with immunohistochemistry." (PMID 34884987, 2021). "In contrast, COMP expression was significantly higher in primary tumor samples, and 55 of the 58 tumor samples (94.8%) were positive for COMP staining." (PMID 33613749, 2021). "Analysis of this material revealed that most of the LNM cells retained the expression of COMP as identified in the primary tumor in both the cancer (73%) and stromal cells (70%)." (PMID 34884987, 2021). "Studies have shown that COMP can increase the ability of tumor cells to degrade the surrounding ECM stroma and enhance EMT by upregulating the expression of MMP9, thereby promoting tumor metastasis." (PMID 32754278, 2020). "In this study, we found that COMP regulated tumor cytoskeletal remodeling and promoted mesenchymal transition by interacting directly with TAGLN." (PMID 32754278, 2020). "Compared with the control group, the COMP-deficient nude mice had slow tumor growth and small tumor volume, and the COMP-overexpressed nude mice exhibited fast tumor growth and large tumor volume." (PMID 32754278, 2020). "In agreement with the previous report, COMP expression was found at a varying intensity in both the stroma and the tumor cells." (PMID 31737569, 2019). "COMP is present on the tumor cell surface and it is also known to interact with several components of cartilage and bone." (PMID 31737569, 2019). "Tumor biopsy samples obtained from the primary tumor (for 34 patients) or metastatic tissue (for 5 patients) were immunohistochemically stained for COMP." (PMID 31737569, 2019). "Theoretically, joint injury leads to increased systemic COMP, which then stimulates tumor progression." (PMID 31413818, 2019). "The effect of COMP on HCC invasive behavior was examined by injecting intravenously in the tail vein with SMMC-7721-rCOMP or SMMC-7721-PBS cells to mimic tumor metastasis." (PMID 30231922, 2018). "Since COMP upregulation was significantly associated with HCC invasion, the role of COMP in tumor migration and invasion was further investigated." (PMID 30231922, 2018). "Functionally, COMP/CD36 signaling caused phosphorylation of ERK and AKT, resulting in the upregulation of tumor-progressive genes such as EMT markers, MMP-2/9, Slug and Twist in HCC cells." (PMID 30231922, 2018). "Analysis of primary HCC serum samples supported the predictive role of COMP in patient’s survival, suggesting that COMP was a promising biomarker and an effective bioactive strategy to combat tumor-progression." (PMID 30231922, 2018). "Most importantly, multivariate Cox proportional hazard regression analysis found tumor size, vascular invasion, and serum COMP high-level to be independent prognostic factors for the overall survival of HCC patients (P < 0.05)." (PMID 30231922, 2018). "Patients with high level of serum COMP showed more unfavorable disease parameters such as higher incidence of vascular invasion and tumor recurrence." (PMID 30231922, 2018). "The expression level of COMP was significantly and positively related to the tumour sizes of PTC patients." (PMID 29967488, 2018). "We should note that similar results were observed in a separate experiment with COMP-Ang1 therapy reducing LM2-4 tumor invasiveness from 52% to 31%." (PMID 27841282, 2016). "Of these probe sets, several genes encoding proteins involved in extracellular matrix (ECM)-tumor interaction and focal adhesion (COL6A3, COL8A1, CTHRC1, THBS2, COMP) were upregulated, whereas ITGA2gene with the same function was downregulated in tumor cells." (PMID 17389037, 2007). "Importantly, COMP is upregulated in NSCLC adenocarcinoma tumor tissue compared to “normal” lung tissue (p < 0.05)." (PMID 40141111, 2025).